SMAD3 (SMAD family member 3)
Diseases named in the same sentence as SMAD3 in open-access papers (continued):
Sharing a sentence is not in itself a finding about the gene and the disease.
tumor (continued). "The same study demonstrated that overexpression of Smad3 enhanced malignancy of primary tumours." (PMID 33809098, 2021). "Additionally, we analyzed the mRNA expression of SMAD3 in 41 paired normal and tumor tissues in patients with CRC obtained from TCGA." (PMID 33036415, 2020). "This novel pathway may be anti-oncogenic in two ways, by desensitizing the tumor cells towards the actions of stromal cell-derived paracrine TGFβ and by promoting their epithelial phenotype via induction of SMAD3." (PMID 33260366, 2020). "Finally, we analysed the activation of SMAD3 in the GARP++ and NT tumours by IHC and observed an increased fraction of cells with high SMAD3-phosphorylation in GARP++ tumours compared to NT tumours." (PMID 33203838, 2020). "Phosphorylation of SMAD3 was significantly reduced in the presence of TMEPAI in the muscles of C26 tumor-bearing mice, and TMEPAI expression also attenuated transcriptional activation of SMAD2/3-target genes in C26 tumor-bearing mice, including Cyr61, and Igfn1." (PMID 33250771, 2020). "Deregulation of components in TGF-β signaling pathway, such as TβRII, Smad3, and Smad4, may be responsible for the loss of TGF-β-mediated tumor-suppressor functions." (PMID 32668597, 2020). "However, in PDAC alterations of TGFβ signaling through the mutation of genes involved in the pathway (e.g., SMAD4, SMAD3, TβR-I, TβR-II, ACVR1B, and ACVR2A), this role is present in 47% of cases, highlighting that TGFβ can sometimes acts as a tumor promoter." (PMID 32429474, 2020). "Thus, it is of significance to find anti-tumor drugs targeting Smad3 or TGF-β/Smad pathway from TCM." (PMID 32477135, 2020). "To clarify the mechanism underlying EVI5-mediated tumor metastasis, we analyzed the molecular expression of TGF-β receptor II, TGF-β receptor I, p-Smad3, Snail, Vimentin, MMP2 and N-Cadherin levels were significantly decreased and E-Cadherin was significantly increased in EVI5-knockdown cells." (PMID 32393392, 2020). "Interestingly, SMAD3 mRNA expression was low in 42.9% (51/119) of Taiwanese CRC tumor tissues and 33.3% of polyps." (PMID 33036415, 2020). "Inhibition of Smad3 in the tumor microenvironment could suppress tumor growth, invasion and metastasis." (PMID 32774166, 2020). "Moreover, SMAD3 hypomethylation was observed in 66.6% (6/9) of polyps, and the methylation level in polyps was between that of normal and tumor tissues." (PMID 33036415, 2020). "Nobiletin has also been shown to inhibit growth of metastatic nodules in the lungs of mice via the TGF-β1/SMAD3 pathway and decrease cell migration, angiogenesis, tumor formation, and progression in the bone osteosarcoma cell line U2OS via ERK and JNK pathways." (PMID 32706791, 2020). "Several studies have reported anti-tumor effects following knockdown of SMAD3." (PMID 32140069, 2020). "Similarly, in the muscles of C26 tumor-bearing mice, where activin A serum concentrations are increased, SMAD3 phosphorylation is significantly reduced by TMEPAI." (PMID 33250771, 2020). "NRP1 may act as a substrate for the regulation of CRT/Smad3 pathway to induce EMT in NPC cells to promote tumor cell migration and invasion." (PMID 31956372, 2020). "Moreover, miR-135-5p was decreased in BC tissues compared to adjacent breast tissues; more interesting, miR-135-5p mRNA levels (Tumor/Normal, T/N) was further decreased in BC patients with lymph node metastasis, while SMAD3 mRNA levels were increased." (PMID 33033523, 2020). "RUNX1 and p-SMAD3 are key genes that promote tumor progression and EMT24,25." (PMID 31754093, 2019). "TRIB3 could interact with SMAD family member 3 (SMAD3) to promote transforming growth factor (TGF)-β induced tumor cell migration and invasion." (PMID 30678233, 2019).
tumor (continued). "Collectively, these observations suggest that promoter silencing of SMAD3 expression may contribute to CAM aberrant phenotype and underlie tumour-promoting properties of CAMs derived from different tissues." (PMID 30624614, 2019). "With the purpose of investigating further the TGF-β/Smad signaling role in SPA tumor development, Smad3 and phosphorylated Smad3 protein levels were measured by immunochemistry in 161 patients with SPAs, including 59 invasive (36.6%) and 102 noninvasive (63.4%) lesions." (PMID 30020466, 2019). "Our results, which suggested that Smad3 is critical for stimulation of tumor growth and metastasis, are in line with the observation that overexpression of a C-terminal truncated dominant negative mutant of Smad3, which inhibited TGF-β-induced migration of MCF10A cells." (PMID 31798766, 2019). "TGF-β is thought to induce phosphorylation of Smad2 or Smad3 in LECs as well as in tumor cells." (PMID 30142879, 2018). "Accordingly, SMAD3 has been found to have both oncogenic and tumor suppressor roles in cancer." (PMID 29130642, 2018). "Since hetero-oligomerization is needed to bind target-specific transcriptional complexes in the nucleus, two different types of phospho-Smad3 transmit different signals, which is consistent with the ability of Smad4 to act as both a tumor repressor and a tumor activator." (PMID 29874844, 2018). "Moreover, we have recently determined that Ahnak acts as a tumor suppressor by activating the TGFβ/Smad3 signaling cascade, which leads to cell cycle arrest in G0/G1 phase and downregulation of c-Myc expression during cell growth." (PMID 30258109, 2018). "However, upregulation TGF-β1 decreased the level of BRCA1 and Smad3 phosphorylation in tumor tissues." (PMID 30594239, 2018). "SMAD3 is a central mediator of the tumour-suppressive function of TGFβ signalling." (PMID 30318519, 2018). "In addition, SMAD3 phosphorylation is higher in muscle from tumor-bearing mice, a critical step in the intracellular signaling pathway that transmits TGFβ signaling to the nucleus." (PMID 29312148, 2017). "It suggested a close link between Smad3 and NK cell development in the tumour microenvironment." (PMID 28262747, 2017). "NK cell population in the Smad3−/− tumour microenvironment is dramatically expanded." (PMID 28262747, 2017). "This may explain the dramatic increase in GFP+ NK1.1+ NK cells at the tumour stroma of the GFP+ Smad3−/− chimeric mice." (PMID 28262747, 2017). "Therefore, to test events further downstream in the TGFβ pathway, we observed that augmentation of phospho-SMAD3, as well as their nuclear translocation, was enhanced in tumor-CD8+ Treg in comparison with control CD8+ T cells." (PMID 28487507, 2017). "We demonstrate that Smad3 phosphorylation switch between the Linker and C-terminal plays crucial role in tumor progression and tumor cell apoptosis and that this switch may strictly be regulated by microRNA-145 expression in HCC." (PMID 29156696, 2017). "Nevertheless, these studies suggested that Smad3 could be an important checkpoint for TGF-β signalling in the tumour microenvironment." (PMID 28262747, 2017). "In addition, the protective effect of Smad3−/− microenvironment was further confirmed on a tumour rechallenging model." (PMID 28262747, 2017). "The splenic NK cells isolated from the B16F10 tumour-bearing Smad3−/− mice also exhibited a significant increase in the ex vivo cytotoxicity against tumour cells with higher levels of INF-γ production when compared with the NK cells obtained from the tumour-bearing Smad3+/+ mice." (PMID 28262747, 2017).
tumor (continued). "Furthermore, systemic treatment with a Smad3 inhibitor can suppress cancer progression by reversing the tumour promoting to an anticancer microenvironment in vivo." (PMID 28262747, 2017). "NK cells exert promising anticancer activity, which may be circumvent by tumour-friendly microenvironment via TGF-β/Smad3 signalling as defined in the present work." (PMID 28262747, 2017). "The population of NK1.1+ CD49b+ NK cells was further increased after cancer inoculation, resulting in a 10-fold increase in NK1.1+ CD49b+ NK cells in the peripheral blood and lung and a 3-fold increase in the spleen compared with the tumour-bearing Smad3+/+ mice." (PMID 28262747, 2017). "However, the potential role of Smad3 in the TGF-β1-dependent tumour microenvironment remains incompletely characterized." (PMID 28262747, 2017). "Our findings suggest that modulating the TGF-β-dependent tumour microenvironments by targeting Smad3 may represent an effective anticancer therapy." (PMID 28262747, 2017). "Moreover, the IHC staining of SMAD3 indicated that SMAD3 was also upregulated in BCa tissues than adjacent non-tumor tissues (P=0.010), and was negatively correlated with miR-323a-3p (r2=0.09142, P=0.0411)." (PMID 28837140, 2017). "Given the importance of miR-1 in aerobic glycolysis in cancer cells, the results prompted us to examine whether activity of the miR-1/Smad3/ HIF-1α axis influenced tumor growth in vivo." (PMID 28471448, 2017). "In line with this notion, we found that cancer cells (B16F10 and LLC) proliferated at the same rate in both Smad3+/+ and Smad3−/− mice during the first week after tumour implantation, but the progression was dramatically inhibited in the Smad3−/− mice from week 2 onwards." (PMID 28262747, 2017). "We propose targeting Smad3-dependent tumour microenvironment may represent an effective anti-cancer strategy." (PMID 28262747, 2017). "Alterations in Smad3 signaling have been attributed to cyclin overexpression, and were directly implicated in the dichotomous role of the TGF-β superfamily in malignancy, enacting both tumor suppressant and tumor promoting behaviors in breast carcinogenesis." (PMID 29137393, 2017). "The encouraging findings from tumour-bearing Smad3−/− mice leads us to further test a hypothesis that targeting Smad3-dependent tumour microenvironment may protect mice against cancer progression." (PMID 28262747, 2017). "Therefore, our findings reveal the unexplored role of Smad3 in NK cell immunity and tumour microenvironment." (PMID 28262747, 2017). "Our results confirm that the expression levels of TLR7, TLR9 and constituents of TGF-β signaling, OAZ1 and P-Para were significantly altered in the tumor tissues of Smad3+/− VD-deprived mice compared to the tumor tissues of wild type VD deprived mice tumor tissues." (PMID 27456065, 2016). "In all CAC tumour models, a mutation in the SMAD3 gene (Ala382Val) was found which was not present in the patient ́s germline DNA." (PMID 27087592, 2016). "We attempted to address the question whether reduction of Smad3 levels promotes de novo tumor formation." (PMID 27588495, 2016). "To examine this hypothesis and further determine whether IL-37b requires Smad3 to carry out its anti-tumor activity, we first evaluated the Smad3 protein level in SMMC-7721 and HepG2 cells." (PMID 27835881, 2016).
tumor (continued). "A low VD regimen promotes tumor growth in the context of TGF-β/Smad3 disruption." (PMID 27456065, 2016). "Taken together, these data indicated that IL-37b may be a direct inhibitor of JNK/pSmad3L/c-myc signaling and promotes Smad3 phospho-isoform signaling shift from JNK/pSmad3L/c-myc oncogenic signaling to pSmad3C/p21 tumor-suppressive signaling." (PMID 27835881, 2016). "Moreover, IL-37 promoted Smad3 phospho-isoform signaling conversion from JNK/pSmad3L/c-Myc oncogenic signaling to pSmad3C/p21 tumor-suppressive signaling." (PMID 27835881, 2016). "In addition, TGF-ß/Smad3 upregulates the expression of a set of genes including Ephrin-A1, which is shown to contribute to the TGF-ß/Smad3 tumor suppressive effects in ER-positive breast cancer." (PMID 27588495, 2016). "Smad3 is a tumor suppressor which inhibits cell proliferation and promotes apoptosis." (PMID 26348837, 2015). "EMT is a process that exerts influence on many molecular, such as TGF-β, E-cadherin, N-cadherin Vimentin, ZEB-1, SMAD-2, SMAD-3, SMAD-7, GLI1 and GLI2; these molecules are closely associated with typical phenotype changes of EMT in tumor cell growth and metastasis." (PMID 25895132, 2015). "SMAD2 and SMAD3 have distinct transcriptional roles in the tumor." (PMID 26146544, 2015). "Moreover, pharmacological reduction of JNK activity not only shifted Smad3 signaling from oncogenesis to tumor-suppression but also inhibited cell proliferation in MUC1-overexpressing HCC cells." (PMID 25714018, 2015). "Moreover, our clinical results of a correlation between FOSL2 and activated Smad3 expression in NSCLC tumours further confirm this conclusion." (PMID 25375657, 2014). "We then showed that loss of tumor suppression in M4 was not due to changes in Smad3 expression, or duration or extent of Smad3 C-terminal phosphorylation, which were similar between all four cell lines." (PMID 24890385, 2014). "It suggests TGF-β/Smad3 may inversely promote the invasion and migration in the late stage of tumor formation." (PMID 24427302, 2014). "In addition to its inhibitory role on cell proliferation, Smad3 can exert a tumor suppression function in hepatic cells by downregulating the antiapoptotic protein BCL2, which results in TGF-β-mediated apoptosis." (PMID 24047375, 2013). "In addition, we also measured the levels of phosphorylated Smad3 at its link region (P-Smad3L) as a function of TGF-β signaling abrogation because nuclear P-Smad3L has been shown to have tumor-promoting activity." (PMID 23704908, 2013). "Moreover, activated myofibroblasts can induce tumor progression in a TGFβ-dependent fashion, and this vicious circle, which involves the TGFβ/Smad3 pathway, is crucial for tumor development." (PMID 22848627, 2012). "However, our results clearly indicate that Nar prevents the EMT process of tumor cells by down regulating TGF-β/Smad3 signaling transduction." (PMID 23300530, 2012). "Inhibition of the TGFβ/Smad3 pathway inhibits stroma cell invasion and tumor growth." (PMID 22848627, 2012). "Additionally, Smad3−/− epidermis and keratinocytes were significantly resistant to the proliferative and proinflammatory effects of TPA, suggesting that Smad3 is critical for tumor promotion by TPA." (PMID 23326666, 2012). "As a major mediator of the TGFβ signaling pathway, Smad3 may be either a tumor suppressor or promoter in a context dependent manner." (PMID 22204491, 2011). "Evaluation in humanized mouse models further confirmed that CD11c overexpression in ESCC resulted in immune evasion, tumor metastasis, and resistance to anti-programmed death ligand 1 (PD-L1) therapy, but could be rescued by combined treatment with anti-phospho-SMAD3." (PMID 41799568, 2026). "Notably, direct upregulation of Smad3 expression in tumor MO-MDSC substantially promoted its differentiation into mature MΦ and DC, whereas inactivation of Smad3 blocked this process, confirming the deficiency of Smad3 as a key factor contributing to impaired MO-MDSC maturation." (PMID 41360769, 2025).
tumor (continued). "Consequently, inhibiting SMAD3 S-palmitoylation may be a pivotal molecular strategy to mitigate tumor spread." (PMID 40066091, 2025). "Notably, SMAD3 expression exhibited significant positive correlations with increasing T stage (r = 0.42, p < 0.001) and N stage (r = 0.38, p < 0.001), emphasizing its biological relevance in tumor progression and invasive capacity." (PMID 40361382, 2025). "Also, tumor cells within hypoxic areas usually have activated TGF-β labeled by p-Smad3." (PMID 40246814, 2025). "Additionally, targeting CDK4 activity to modulate tumor-suppression SMAD3 may represent a promising strategy for cancer patients." (PMID 38528618, 2024). "Therefore, targeting Smad3 S-palmitoylation could be a crucial molecular approach in combating tumor metastasis." (PMID 38415253, 2024). "Even though both control and Ptger4-KO tumor cells showed an increase in p-SMAD3 protein upon TGF-β and PGE2 exposure, EP4-deficient tumor cells had lower levels of p-SMAD3 compared with the controls, with and without treatment, indicating a deficiency in TGF-β signaling." (PMID 39298269, 2024). "Similarly, lincNMR is induced by TGF-β and associates with Smad2 or Smad3 to promote the expression of APOBEC3B, which may contribute to tumor malignancy." (PMID 38569937, 2024). "In addition, high SMAD3 expression was found in CAFs in the tumor microenvironment." (PMID 38493128, 2024). "Furthermore, given the interest in neutrophils for the tumor-specific delivery of anticancer drugs, then utilizing Smad3-KO neutrophils might aid in this effort." (PMID 37002229, 2023). "While TGF-β/Smad3 signaling suppresses natural killer cell (NK cell) activity and promotes the accumulation of cancer-associated fibroblasts, the contribution of TGF-β/Smad3 signaling in the polarization of TANs and tumor growth remains unknown." (PMID 37002229, 2023). "In addition, Smad3-KO neutrophils show the enhanced killing of tumor cells in vitro." (PMID 37002229, 2023). "Inhba siRNA significantly reduced SMAD3 phosphorylation but p38 phosphorylation was statistically not‐significant when compared to the Sc‐si group, suggesting that activin A might act through SMAD3 phosphorylation during orthotopic tumor growth." (PMID 37083240, 2023). "However, the main biological effects of TGFβ are inhibition or promotion of proliferation, differentiation, apoptosis, cell dormancy, autophagy and cellular senescence; reduced levels of SMAD3 in RAMA 37-28 cells can suppress the function of TGF-β-induced expression of tumor suppressor genes." (PMID 37239828, 2023). "To further confirm Kindlin-2 involvement in mammary epithelial cells to regulate tumor growth, we isolated mammary epithelial cells from wild-type or K2-deficient mice and treated them with either TGF-β or EGF, and subsequently measured their activation of either SMAD3 or ERK1/2, respectively." (PMID 35158908, 2022). "Indeed, they also reported that TGF-β may regulate galectin-9 (Gal-9) expression by the Smad3 pathway in tumor cells." (PMID 35432324, 2022). "Further, a frequent hallmark of tumor cells is overexpression and/or amplification of growth factor receptors on cell surfaces, resulting in aberrant constitutive linker phosphorylation of Smad3 in the absence of pro-inflammatory cytokines." (PMID 35682957, 2022). "Hence, these results establish that the response of cancer cells upon extrinsic TGF-β stimulation was not unique, but rather it took advantage of the intrinsically activated SE to adopt the TGF-β/SMAD3 signaling pathway for regulating the tumor microenvironment and metastasis in LUAD." (PMID 35982471, 2022). "A motility gene expression study indicated that SMAD3 selectively increased the expression of ITGB2 and VIM, two genes that were found to be implicated in hypoxia-induced cell invasion and associated with tumor progression and metastasis in cohorts of cancer patients." (PMID 35681731, 2022). "FOXO1/3 and SMAD3 pathways could promote the tumor development." (PMID 35017463, 2022).